CLDN1 (claudin 1)
Diseases named in the same sentence as CLDN1 in open-access papers (continued):
Sharing a sentence is not in itself a finding about the gene and the disease.
psoriasis (11 papers, 2014 to 2025). An autoimmune condition characterized by red, well-delineated plaques with silvery scales that are usually on the extensor surfaces and scalp. "Our results indicate that claudin-1 is an important tight junction protein in psoriasis pathogenesis, as its aberrant distribution is associated with disease severity." (PMID 39582772, 2024). "This study aimed to estimate serum IL-17A and Claudin-1 levels, investigate their correlation, and evaluate their diagnostic significance as potential blood-based biomarkers in psoriasis." (PMID 35340911, 2022). "The mislocalization of CLDN1 has been associated in various dermopathies, including the inflammatory disease, psoriasis." (PMID 25340345, 2014). "Therefore, the process of differentiation in psoriasis skin and the signaling associated with it, could contribute to claudin-1 aberrant distribution." (PMID 39582772, 2024). "Altered expression of claudin-1 in psoriasis is presumably due to rapid turnover and impaired differentiation of keratinocytes in the upper epidermis." (PMID 37707681, 2024). "By using immunofluorescence, we identified and located S. aureus and SEB in the epidermis and dermis of patients and distinguished three groups of psoriasis patients with different involvement of the barrier integrity given by claudin-1." (PMID 39582772, 2024). "Immunohistochemically analysis of claudin-1 showed that the transformation of skin model to the psoriasis phenotype by cytokine mixture treatment led to a significant decrease in the total claudin-1 signal." (PMID 37707681, 2024). "Considering these insights from prior research, our next aim was to investigate the relationship between RTCA results and the CLDN1 gene expression regulation within psoriasis-like inflamed keratinocytes, comparing them to their respective controls." (PMID 38132145, 2023). "Previous studies have investigated Claudin-1 in skin, but serum Claudin-1 levels remained unknown in psoriasis, while our results remind us of serum Claudin-1 as a potentially sensitive diagnostic marker for distinguishing early-onset psoriasis from late-onset psoriasis." (PMID 35340911, 2022). "These preliminary results suggest that the serum Claudin-1 as a potential biomarker and the relationship and possible regulatory interactions between IL-17A and Claudin-1 in psoriasis are distinguishable by age of onset." (PMID 35340911, 2022). "Currently, studies regarding Claudin-1 in psoriasis have been focused on ex vivo experiments of human or animal skin and in vitro experiments of keratinocytes." (PMID 35340911, 2022). "ROC curve analysis indicated the serum IL-17A, serum Claudin-1, and combination of IL-17A and serum Claudin-1 for predicting psoriasis with the areas under the curve (AUC) of 0.951 (p < 0.0001), 0.709 (p = 0.0119), and 0.949 (p < 0.0001), respectively." (PMID 35340911, 2022). "In our current study, combinatorial biomarkers of serum IL-17A and Claudin-1 are potential predictive markers for psoriasis and Claudin-1 for identification onsets of psoriasis, although little is known about the role of Claudin-1 in the age at onset." (PMID 35340911, 2022). "Mislocalization of CLDN1 is a feature of a number of cutaneous diseases such as psoriasis, and in a number of cancers." (PMID 25340345, 2014). "In psoriasis, the claudin-1 expression is decreased compared to healthy skin, although the precise mechanisms remain unclear." (PMID 39582772, 2024). "Claudin-1 that are normally found in all layers of the epidermis was observed at decreased levels, especially in the lowermost (stratum basale) but also in the uppermost layers (stratum corneum) of the epidermis in early-stage psoriasis." (PMID 37707681, 2024). "Additionally, the reduction in nCI values in psoriasis-like KCs correlated with a significant down-regulation of CLDN1 gene expression, suggesting an induced epidermal barrier dysfunction in KCs by psoriasis-like inflammation." (PMID 38132145, 2023).
psoriasis (continued). "Moreover, ROC curves analysis showed outstanding performance of serum Claudin-1 for separating early-psoriasis from late-onset psoriasis." (PMID 35340911, 2022). "Rather promisingly, new data on the roles of IL-17A and Claudin-1 and on the regulation of Claudin-1 by IL-17A in psoriasis may indicate new therapeutic approaches." (PMID 35340911, 2022). "Moreover, the potential role in distinguishing between early-onset and late-onset psoriasis: we obtained serum IL-17A, serum Claudin-1, and their combination AUC of 0.590 (p = 0.3126), 0.741 (p = 0.0045), and 0.741 (p = 0.0067), respectively." (PMID 35340911, 2022). "The aim of the current investigation was to estimate serum IL-17A and Claudin-1 levels in psoriasis, detect their correlation with disease severity, and examine whether they are blood-based candidate biomarkers associated with psoriasis and subtypes." (PMID 35340911, 2022). "The question whether IL-17A regulates Claudin-1 remains unanswered; findings that they are correlated should be met with caution: further prospective studies are required, especially in psoriasis." (PMID 35340911, 2022). "Statistical analyses were performed to determine differences in serum levels of IL-17A and Claudin-1, their bivariable correlation with psoriasis severity, as Psoriasis Area Severity Index (PASI), and their predictive abilities using receiver operating characteristic (ROC) curves." (PMID 35340911, 2022). "Significantly higher IL-17A and lower Claudin-1 levels were found in psoriasis (p < 0.05)." (PMID 35340911, 2022). "Remarkably, the combination of IL-17A and Claudin-1 (AUC: 0.741, p = 0.0067) almost performed identically to Claudin-1 alone (AUC: 0.741, p = 0.0045), while IL-17A (AUC: 0.590, p = 0.3126) had poor performance separating early-onset psoriasis from late-onset psoriasis." (PMID 35340911, 2022). "The combination of IL-17A and Claudin-1 exhibited equal performance in discriminating psoriasis from controls (AUC: 0.949, p < 0.0001), with the model comprising only IL-17A (AUC: 0.951, p < 0.0001), which performed better than the model including just Claudin-1 (AUC: 0.709, p = 0.0119)." (PMID 35340911, 2022). "However, none of the models, IL-17A alone (AUC: 0.553, p = 0.5596) or just Claudin-1 (AUC: 0.518, p = 0.8539) or their combination (AUC: 0.559, p = 0.5225), was shown to have better discriminatory performance to discriminate mild psoriasis from moderate-to-severe psoriasis." (PMID 35340911, 2022). "Nevertheless, it is important to note that the downregulation of CLDN1 gene expression is most likely not the only factor contributing to the lower CI/nCI values observed in psoriasis-like KCs." (PMID 38132145, 2023). "Serum Claudin-1 (but not IL-17A) levels show a highly significant difference (p = 0.008) between early-onset and late-onset psoriasis patients." (PMID 35340911, 2022). "PASI did not correlate significantly with either IL-17A or Claudin-1 in psoriasis and their subtypes." (PMID 35340911, 2022). "Notably, both serum IL-17A and Claudin-1 do not correlate with PASI in psoriasis and in its subgroups, except for correlation in late-onset psoriasis." (PMID 35340911, 2022). "However, none of the serum IL-17A, serum Claudin-1, and their combination was well-performed discriminating mild psoriasis from moderate-to-severe psoriasis with AUC of 0.553 (p = 0.5596), 0.518 (p = 0.8539), and 0.559 (p = 0.5225), respectively." (PMID 35340911, 2022). "The combinatorial biomarkers of serum IL-17A and Claudin-1 may serve as a good predictor for psoriasis, while they each or combined could not be candidate biomarkers assessing psoriasis severity." (PMID 35340911, 2022). "Besides, the significance of serum Claudin-1 in psoriasis is not known yet." (PMID 35340911, 2022).
thyroid cancer (11 papers, 2017 to 2025). "First, SS promotes CLDN1, which is significantly negatively associated with the risk of thyroid carcinoma (p(HR) = 0.031), suggesting a potential beneficial role in TC survival through the SS-CLDN1-TC pathway." (PMID 39928612, 2025). "Survival analysis revealed that only CLDN1 is significantly negatively associated with the risk of thyroid carcinoma (p(HR) = 0.031)." (PMID 39928612, 2025). "While data regarding thyroid cancer are scarce, the association between miRNA and claudin-1 has been demonstrated in other thyroid pathologies, including Hashimoto’s thyroiditis (HT)." (PMID 39458944, 2024). "In general, low expression of TJs is observed in highly metastatic cancer cells, and dedifferentiation of thyroid carcinomas is associated with a decrease in claudin-1, -4, and -7 expression." (PMID 36980530, 2023). "Claudin-1 levels increased stepwise during the progression from normal thyroid tissue to thyroid cancer, but the mechanisms underlying those changes remain unknown." (PMID 39458944, 2024). "To highlight the potential role of claudin-1 and claudin-4 targeted therapies in thyroid cancer, we revised and summarized relevant studies published between 2019 and 2024." (PMID 39458944, 2024). "To date, several preclinical studies exploring the role of claudin-1 targeted approaches in thyroid cancer have been reported." (PMID 39458944, 2024). "We reviewed the literature and summarized the previous reports to highlight the potential role of claudin-1 and claudin-4 targeted therapy in thyroid cancer." (PMID 39458944, 2024). "In this study, we investigated the expression patterns of claudin-1 and claudin-4 in thyroid pathologies, discussed their links with the pathogenesis of thyroid cancers, and reviewed the therapeutic potential of targeting claudins in cancers." (PMID 39458944, 2024). "For instance, claudin-1 overexpression promoted thyroid cancer cell migration and invasion, while its knockdown reduced the viability and growth of thyroid tumors." (PMID 39458944, 2024). "High CLDN1 expression is found in thyroid carcinomas and correlates with shorter overall survival of patients with gastric and ovarian cancers." (PMID 37318881, 2023). "The overexpression of Claudin-1 has been reported to correlate with cell proliferation and aggressiveness in thyroid carcinoma." (PMID 35818041, 2022). "Another study described the reduced expression of CLDN-1 in follicular carcinomas vs adenomas, specifically in the poorly-differentiated and undifferentiated types of human thyroid carcinomas." (PMID 31952355, 2020). "Despite that, targeting circ_0027446 or delivering tumor-suppressing miRNA-129-5p to cancer cells may be a potential anti-claudin-1 therapy in thyroid cancer." (PMID 39458944, 2024). "This study explored the concept of targeting claudin-1 and claudin-4 in thyroid cancer." (PMID 39458944, 2024). "Available preclinical studies indicate that targeting claudins, especially claudin-1, may be a promising therapeutic approach in thyroid cancer." (PMID 39458944, 2024). "Targeting claudin-1 and claudin-4 is a promising approach to managing thyroid cancers." (PMID 39458944, 2024). "Clarifying the role of claudin-1 and claudin-4 in the pathogenesis of thyroid cancers may improve our understanding of tight junction proteins’ role in early metastasis." (PMID 39458944, 2024). "The role of Cldn1 in follicular type of thyroid cancer was well described." (PMID 31825142, 2020). "The data showed that Mut3 enables binding of cCPE to Cldn1‐expressing thyroid cancer cells." (PMID 31825142, 2020). "Thus, directed modification of CPE enables eradication of tumor entities that cannot be targeted by CPEwt, for instance, Cldn1‐overexpressing thyroid cancer by using the novel CPE‐Mut3." (PMID 31825142, 2020). "However, for PTC, the most common type of thyroid cancer, the Cldn1 expression, and its role in pathogeny are currently poorly characterized." (PMID 31825142, 2020).
thyroid cancer (continued). "Furthermore, in contrast to CPEwt, CPE‐Mut3 was cytotoxic for K1 thyroid cancer cells expressing endogenous Cldn1." (PMID 31825142, 2020). "The expression level of CLDN1 is increased in colon, stomach, and thyroid cancer tissues." (PMID 32824620, 2020). "Claudin-1 and claudin-4 expressions were negative in medullary carcinoma and most anaphylactic carcinoma samples, indicating tight junction loss in aggressive thyroid cancers, suggesting that the downregulation of claudins is associated with the de-differentiation of thyroid cancer." (PMID 39458944, 2024). "In case of thyroid cancer and NSCLC, overexpression and extrajunctional mislocalization of Cldn1, with impact on cell–cell contacts and proliferation, is a specific hallmark." (PMID 31825142, 2020). "Another study about the role of CLDN-1 in follicular-cell derived thyroid carcinoma cell lines (FTC-133 and FTC-238) found higher expression of CLDN-1 in the nuclei of FTC-238 cells as compared to the FTC-133 cells." (PMID 31952355, 2020). "The levels of claudin-1 varied significantly between thyroid cancers—claudin-1 was overexpressed in PTC, but MTC and ACT did not express claudin-1." (PMID 39458944, 2024). "In particular, binding to Cldn1 expressed in NSCLC and thyroid cancer was intended." (PMID 31825142, 2020). "In addition, CLDN1 was highly expressed in not only other NSCLC types but also colon, stomach, and thyroid cancer tissues, suggesting that PMTPV may enhance the chemosensitivity of these cancer cells." (PMID 32824620, 2020).
invasive breast carcinoma (10 papers, 2005 to 2024). A carcinoma that infiltrates the breast parenchyma. "Since many genes have been shown to undergo deregulation through splicing and mis-splicing events in cancer, the current study was undertaken to investigate the occurrence of transcript variants for CLDN1 in human invasive breast cancer." (PMID 27649506, 2016). "Suggested to be a tumor suppressor, down regulation of the claudin 1 gene (CLDN1) has been associated with estrogen receptor (ER) positivity and poor prognosis in invasive breast cancer." (PMID 27649506, 2016). "In the present study, we investigated whether CLDN1 transcript variants occur in human invasive breast cancers." (PMID 27649506, 2016). "Whereas claudin-1 expression is downregulated in many invasive breast carcinomas and tends to have an overall worse survival compared to luminal type." (PMID 40034931, 2024). "We, hereby, assessed the IHC expression of cyclin D1 and claudin-1 in invasive breast carcinoma of women from a rural part of northern India and correlated with different clinicopathological variables." (PMID 40034931, 2024). "CLDN1 upregulation following neoadjuvant chemotherapy was previously observed in patients with invasive breast cancer." (PMID 37041570, 2023). "Methylation of the claudin 1 promoter CpG island in invasive breast carcinomas and normal breast tissue." (PMID 23844228, 2013). "We have shown that CLDN1 was amplified and upregulated in the invasive breast carcinoma." (PMID 26067567, 2015). "By using immunohistochemistry, we have analysed claudin-1, -3, -4, and -7 tight junction proteins expression and their prognostic value on IMPCs and compared them to invasive breast carcinomas of no special type (IBC-NST) tumors." (PMID 39687048, 2024). "While most invasive breast cancers exhibit a down regulation or absence of claudin 1, some aggressive subtypes that exhibit high claudin 1 levels have now been described." (PMID 26633531, 2015). "We demonstrated that immunohistochemically detectable CLDN1 protein is absent or its expression is markedly decreased in the majority of different types of invasive breast carcinomas as compared with normal ducts." (PMID 15743508, 2005). "In contrast, absent or decreased expression of CLDN1 in invasive breast carcinomas was demonstrated at both mRNA and protein levels." (PMID 15743508, 2005).
nasopharyngeal carcinoma (10 papers, 2010 to 2025). A carcinoma arising from the nasopharyngeal epithelium. "Cytoplasmic and nuclear Claudin-1 delocalization was associated with decreased apoptosis in nasopharyngeal carcinoma cell lines." (PMID 35432533, 2022). "Additionally, they found that Claudin-1 facilitated the migration and invasion of nasopharyngeal cancer cells through activation of the Wnt/β-catenin signaling pathway." (PMID 40066340, 2025). "In line with this, CLDN1 overexpression associates with high grade OSCC perineural invasion and shown to upregulate EMT marker Vimentin in conjunction with nuclear translocation of β-catenin in nasopharyngeal carcinoma." (PMID 38942893, 2024). "In nasopharyngeal carcinoma (NPC) cells, up-regulated CLDN1 expression confers resistance to cell death." (PMID 28055967, 2017). "The serglycin/CD44 signaling axis induces the expression of Nanog and activates NF-κB/claudin-1 axis in NSCLC and triggers MAPK/β-catenin signaling in nasopharyngeal cancer cells to foster EMT, cancer cell stemness, and drug resistance." (PMID 35494005, 2022).
squamous cell carcinoma (10 papers, 2008 to 2025). A carcinoma arising from squamous epithelial cells. "Tumor epithelial clusters expressed canonical squamous carcinoma markers such as CLDN1, LAMB3, TP63, CDKN2A, EPCAM, and SERPINB2, validating their malignant identity, while stromal and immune subsets displayed expected transcriptional programs." (PMID 41510303, 2025). "A comparison of claudin-1 expression and localization in squamous cell carcinoma (SCC) and healthy skin tissue was performed by immunostaining analysis." (PMID 36232536, 2022). "For instance, CLDN5 expression was detected in most of adenocarcinomas, but squamous cell carcinomas was detected CLDN1 overexpression." (PMID 28160565, 2017). "On the contrary, CLDN1 positivity predicted a better survival in adeno and squamous cell carcinoma." (PMID 33597819, 2021). "IGF-1 has been shown to increase transepithelial electrical resistance (a measure of barrier function) by regulating occludin and claudin-3 in submandibular gland cells, zona occludens (ZO)-1 in A431 human epidermoid carcinoma cells and claudin-1 in osteoblast cells." (PMID 24618563, 2014). "The positive control, obtained from the epidermoid carcinoma cell line (A431), demonstrated a strong expression of both claudin-1 and occludin in comparison to HT-29 cells indicating that HT-29 cells might have the low endogenous expression of tight junction proteins." (PMID 34646849, 2021). "We also analysed SR-BI and CLDN-1 expression in the same cell lines, and the lack of interaction between CD81 and E1E2 glycoproteins cannot be correlated with the absence of these molecules (see squamous carcinoma, A431)." (PMID 18382656, 2008).